WDR5 (WD repeat domain 5)
Diseases named in the same sentence as WDR5 in open-access papers (continued):
Sharing a sentence is not in itself a finding about the gene and the disease.
cancer (continued). "The WDR5 WIN site, one of the two well-known binding sites of WDR5, has been found to interact with various ligands, exerting different physiological functions, many of which are linked to cancer development." (PMID 38744853, 2024). "Those WDR5 inhibitors reduce the proliferation of cancer cells." (PMID 37568727, 2023). "WDR5 has been overexpressed in pancreatic cancer, leukemia, colorectal cancer and other cancers." (PMID 36770884, 2023). "Therefore, novel and potentially impactful findings—such as the discovery of an important c-MYC cofactor like WDR5—must be investigated in the context of cancers that are maintained by N-MYC to fully understand any broad-reaching significance." (PMID 37336886, 2023). "Therefore, most likely, WDR5 is recruited by some specific transcriptional factors to co-promote the expression of stem-like traits-related or drug-resistant genes in cancer treatment and then affects the prognosis of cancer patients." (PMID 37708089, 2023). "Finally, the development of WDR5 inhibitors and degraders is at an early stage but still with great potential to target several cancers." (PMID 37568727, 2023). "Our results showed that WDR5 knockdown or inactivity reversed the down-regulated sensitivity of CRC cells to oxaliplatin caused by TOX3 overexpression, while WDR5 overexpression desensitized cancer cells to oxaliplatin based on TOX3 knockdown." (PMID 37708089, 2023). "Therapeutic application of WIN site inhibitors is complicated by the disparate functions of WDR5, but is generally guided by two assumptions—that WIN site inhibitors disable all functions of WDR5, and that changes in H3K4me drive the transcriptional response of cancer cells to WIN site blockade." (PMID 35115608, 2022). "Considering WDR5 is a promising target for pharmacological inhibition in cancer 40, WDR5 inhibitor may also be feasible for CRC patients." (PMID 35371306, 2022). "The suppression of WDR5 signal can repress the growth of cancer cells." (PMID 36483601, 2022). "WDR5 is also a prominent target for pharmacological inhibition in cancer." (PMID 35115608, 2022). "WDR5 has, thus, emerged as an attractive target for cancer therapeutics." (PMID 34299488, 2021). "Our results demonstrate that MS67 offers a potential therapeutic avenue for WDR5-dependent cancers." (PMID 34586829, 2021). "However, inhibitors that block protein-protein interactions (PPIs) between WDR5 and its binding partners exhibit modest cancer cell killing effects and lack in vivo efficacy." (PMID 34586829, 2021). "In cancer cells where the molecular clock is retained, oscillation of chromatin state, availability of chromatin-binding proteins like WDR5, and higher-level chromatin organization may still occur." (PMID 34299381, 2021). "MYC relies on WDR5 for binding to high affinity sites, and disruption of the MYC-WDR5 interaction may be a viable approach to treating MYC-driven cancers." (PMID 34299381, 2021). "Additionally, by forming protein complexes with other proteins such as MYC, WDR5 induces the expression of key oncogenes, leading to tumor initiation, cell cycle progression, DNA replication, invasion, and cancer metastasis." (PMID 34201935, 2021). "Besides these physiological and biological roles of WDR5, it also plays important roles in sets of pathology development, especially in cancer." (PMID 33668971, 2021). "Collectively, our results demonstrate that structure-based design can be an effective strategy to identify highly active degraders and suggest that pharmacological degradation of WDR5 might be a promising treatment for WDR5-dependent cancers." (PMID 34586829, 2021). "WDR5 contributes to tumorigenesis in a wide range of human cancers." (PMID 34586829, 2021). "In addition to degrading total and chromatin-bound WDR5, MS67 also decreased chromatin-bound fractions of MLL complex components, such as MLL, RBBP5, and Menin, and c-MYC, another WDR5 partner in cancer." (PMID 34586829, 2021).
cancer (continued). "Moreover, HBx can directly interact with WDR5 by binding with its α-helix domain, thus affecting WDR5 localization on the chromatin genome and promoting the expression of genes important for cancer progression." (PMID 34070716, 2021). "Furthermore, WDR5/KMT2 complexes have been shown to confer cancer cells with resistance to genotoxic stress by promoting the expression of many genes in the glutathione (GSH) metabolic cascade." (PMID 33302406, 2020). "The series reported here furthers the understanding of the WDR5 WIN site and functions as a starting point for the development of more potent WDR5 inhibitors that may serve as cancer therapeutics." (PMID 31768400, 2019). "The purpose of this review is to describe the current molecular understandings of WDR5, discuss how it participates in diverse cellular processes, and highlight drug discovery efforts around WDR5 that may form the basis of new anti-cancer therapies." (PMID 29385767, 2018). "Given that WDR5 itself is essential in most cancer cells, and that is involved in so many functions, one might naively expect Win site inhibitors to be toxic to all cells." (PMID 29385767, 2018). "As reported, WDR5 is a major driver of cell progression in various cancer types." (PMID 28300833, 2017). "Alternatively, as the genes encoding the other components of the MLL2 complex (MLL2, ASH2, RBQ3) are also reported to be amplified in some cancers, we could investigate their prognostic value and potential interactions with WDR5 during breast carcinogenesis." (PMID 26355959, 2015). "Furthermore, we identified some target genes of WDR5, and further investigation is underway to elucidate how WDR5 regulates target genes contributing to cancer development." (PMID 25656485, 2015). "Furthermore, we asked whether there exists a common effect of WDR5 PROTAC among different cancer types." (PMID 40267190, 2025). "Leveraging on the cancer cell line dependency dataset, the medicinal chemistry tool compounds and integrated genomics and molecular oncology approaches, we here report the tryptophan-aspartic acid (W-D) repeat containing protein 5 (WDR5) to be a vulnerability and drug target in SS." (PMID 40267190, 2025). "Therefore, WDR5 is expected to become an effective therapeutic target for cancer." (PMID 39350229, 2024). "However, whether PDPK1 and WDR5 contribute to similar mitotic gene regulation in MYC-overexpressing cancers remains unclear." (PMID 38605297, 2024). "Mechanism may be trumped by safety and efficacy, but as it also sets expectations for utility and influences clinical implementation, it is worth evaluating how well the notion of WDR5 inhibitors as an epigenetic anti-cancer therapy holds up when viewed a decade from its inception." (PMID 38202281, 2024). "The synergistic anchoring of TOX3 with WDR5 at the promoter of ABCG2 causes the enrichment of histone H3K4 tri-methylation, thereby further promoting ABCG2 transcription and expression and subsequent cancer stem-like traits expansion and drug sensitivity deregulation." (PMID 37708089, 2023). "Most of the studies proved that suppressed Wdr5 may be a new therapeutic target in cancers." (PMID 36358925, 2022). "Aberrant WDR5 expression itself may occur in a number of cancer types." (PMID 36043466, 2022). "By forming protein complexes with other proteins such as Myc, WDR5 induces transcriptional activation of key oncogenes, tumor cell cycle progression, DNA replication, cell proliferation, survival, tumor initiation, progression, invasion, and metastasis of cancer of a variety of organ origins." (PMID 30488017, 2018). "More importantly, our results indicate that the WDR5-MHC I pathway and/or WDR5–immune checkpoint/cytokine pathways should be selectively targeted respectively in WDR5-based epigenetic cancer immunotherapy." (PMID 39201460, 2024).
cancer (continued). "In this study, we uncovered the molecular mechanism of how PTENα/β-NTE promotes cancer progression and identified a novel binding motif, SSSRRSS, a common fragment in the PTENα/β-NTE domain that interacts with the WDR5 WIN site." (PMID 38744853, 2024). "TOX3 overexpression reversed the inhibition at the transcription of ABCG2, the expression of cancer stem-like traits-related genes, clonogenicity, spheroid formation, and CSC frequency induced by WDR5 knockdown, and vice versa." (PMID 37708089, 2023). "By contrast, the transcription activity of ABCG2, spheroid formation, clonogenicity, and the expression of cancer stem-like traits-related genes was respectively enhanced, and the sensitivity to oxaliplatin was attenuated, in CRC cells by WDR5 overexpression." (PMID 37708089, 2023). "By targeting WDR5, it is possible to disrupt the activation of MYC and potentially limit cancer progression." (PMID 37568727, 2023). "WDR5 is an independent prognostic biomarker for poor prognosis of BM from NSCLC, with the cancer-related odds as 2.48." (PMID 36249032, 2022). "Abnormal expression of PRMT5, MEP50, or WDR5 are found in many cancers and often correlated with malignant progression of tumor indicates that PRMT5/MEP50/WDR5 complexes plays an important role in cancer progression." (PMID 35987690, 2022). "Interactions between WD40 repeat domain protein 5 (WDR5) and its various partners such as mixed lineage leukemia (MLL) and c-MYC are essential for sustaining oncogenesis in human cancers." (PMID 34586829, 2021). "Recent studies indicate that WDR5 also interacts with long, noncoding RNAs (lncRNAs), such as HOXD-AS1 and HOTTIP, to facilitate gene transcription in cancer via lncRNA-guided histone H3K4 trimethylation." (PMID 34154613, 2021). "Compound 150 shows exceptionally tight binding to WDR5, strong inhibition of MLL1 histone methyltransferase activity, and excellent activity against MYC-driven cancer cell lines." (PMID 34299488, 2021). "Cutting edge drug discovery approaches, such as NMR-based fragment screening, also represent attractive strategies for the exploitation of WDR5, and, by extension, MYC, for cancer therapy." (PMID 34299488, 2021). "Recent studies indicate WDR5 as a promising cancer target beyond MLL-r cancers, with the potential for WDR5 inhibitors to deliver clinical impact." (PMID 31768400, 2019). "WBM-site inhibitors therefore have potential as anticancer agents—being able to directly disrupt the interaction of c-MYC to WDR5 and thus impede the MYC function in cancer cells." (PMID 31768400, 2019). "Additional studies on the effect of mutations in KMT2/MLL proteins and WDR5 will provide further understanding of the role of WDR5 and the COMPASS complex in cancer." (PMID 29925347, 2018). "HOTTIP, which lies at the 5’ tip of the HOXA locus and drives gene transcription by binding to the WD repeat domain 5 (WDR5)/mixed lineage leukemia (MLL) complex, has been identified as a critical factor with tumor progression in different cancers." (PMID 29415429, 2018). "To address this question, we individually knocked down H2A.Z, WDR5, and BPTF in LD611 cancer cells and looked at the expression of H2A.Z target genes." (PMID 24279307, 2013). "Interactions between the WBM site of WD repeat domain 5 (WDR5) and MYC are believed to play a role in cancer and inhibition of the PPI may have therapeutic potential." (PMID 40443986, 2025). "This study highlights the intricate and complex nature of mitotic gene regulation in cancer cells marked by MYC amplification and provides a foundation for future studies to determine the exact mechanism by which N-MYC, WDR5, and PDPK1 converge on cell cycle related processes." (PMID 38605297, 2024).
cancer (continued). "In fact, WDR5 also interacts with MYC, a well-known oncoprotein broadly overexpressed in some cancers, through its WBM site to promote tumorigenesis, and other proteins through its WIN site and these interactions are extensively reported to be involved in tumor progression." (PMID 38744853, 2024). "In mammals, WDR5, a key component of the COMPASS-related complexes, has been reported to be absolutely required for the regulation of Hox genes expression during mammalian embryo development and cancer progression via different mechanisms." (PMID 39526890, 2024). "For example, among nonkinase targets,the WDR5 protein, which regulates transcription and is a cancer therapeutictarget, has two cysteines within strikingdistance of some inhibitors, making it a potential candidate for sitespecific cross-linking." (PMID 38947214, 2024). "Given the results above, we assumed that WDR5 tri-methylates H3K4 at ABCG2 promoter to further recruit TOX3 resulting in the up-regulation of ABCG2 transcription and ultimately in the development of cancer stem-like traits and drug resistance." (PMID 37708089, 2023). "MS67 is more effective than WDR5 inhibitors in effectively and selectively depleting WDR5, inhibiting transcription of WDR5 regulatory genes, reducing MLL complex components and chromatin binding parts of c-MYC, and inhibiting the proliferation of cancer cells." (PMID 36770884, 2023). "Targeting WDR5 may, thus, provide a strategy to exploit MYC, a critical driver of many cancers that has remained difficult to target directly due to its lack of defined small molecule binding sites." (PMID 34299488, 2021). "We found that MS67, but not MS67N, effectively reduced WDR5 protein expression and suppressed the growth of these primary cancer cells in vitro." (PMID 34586829, 2021). "Furthermore KMT2D can catalyze H3K4 monomethylation by stabilizing the WDR5 protein and enhancing the interactions between components within the KMT2D–enzyme complex in an LLPS-dependent manner, thus promoting cancer progression." (PMID 34758724, 2021). "A higher level of WDR5 protein was detected in cancer tissues than in adjacent normal or benign prostate tissues." (PMID 33754029, 2021). "WDR5 has been found to bind many lncRNAs, including HOTTIP, a lncRNA regulating the expression of HOX genes, the upregulation of which is characteristic of various types of human cancers." (PMID 33302406, 2020). "Similar to WDR5, the expression of RBBP5 is also increased in many cancers." (PMID 33302406, 2020). "The interaction of WDR5 with lncRNAs facilitates the recruitment of WDR5/KMT2A complexes and lncRNA-mediated gene transcription and determines the role of WDR5 as a tumorigenic agent in many cancers." (PMID 33302406, 2020). "The WDR5 protein may also recruit KMT2 complexes to chromatin by recognizing various histone modifications, and this mechanism may contribute to its role in cancer." (PMID 33302406, 2020). "WDR5 is a principal component of the H3K4me3 writer complex MLL–SET1 and interacts with MYC oncoprotein, allowing MYC to select its target genes and alter their expression epigenetically in cancer." (PMID 31920530, 2019). "Previous works also suggest that WDR5 plays a critical role in the regulation of tumor cell migration, as well as of invasion in a zebrafish transplantation model, and in the control of metastasis formation by inducing EMT in various cancers." (PMID 31752957, 2019). "In summary, our findings provide atomic-level insights into the molecular mechanisms underlying the non-canonical mitotic function of the MLL/WDR5 complex and highlight WIN-S7 sites as promising therapeutic targets for diseases associated with chromosomal instability, such as cancers." (PMID 40302551, 2025).
cancer (continued). "MS67 potently and selectively depleted WDR5 and was more effective than WDR5 PPI inhibitors in suppressing transcription of WDR5-regulated genes, decreasing the chromatin-bound fraction of MLL complex components and c-MYC, and inhibiting the proliferation of cancer cells." (PMID 34586829, 2021). "However, these inhibitors that block PPIs between WDR5 and its binding partners in general exhibit only partial or modest effects on cancer cells and are not efficacious in vivo in preclinical cancer models." (PMID 34586829, 2021). "The unique dependence of MLL1 activity on WDR5 may be of therapeutic relevance, as we and others have shown that pharmacological targeting of the MLL interaction site on WDR5 can functionally antagonize MLL1 in cancers that are dependent on MLL1 activity." (PMID 31400120, 2019). "Treatment with OICR-9429, a small-molecule antagonist of the WDR5-MLL interaction, inhibits the β-catenin/JDP2/PRMT5 complex-reestablished GSH metabolism, leading to a lethal increase in the already-elevated levels of ROS in the genotoxic-agent treated cancer cells." (PMID 31434880, 2019). "We discovered potent WIN site inhibitors and found that they kill MLL cancer cells not through changes in histone methylation, but by displacing WDR5 from chromatin at protein synthesis genes, choking the translational capacity of these cells, and inducing death via a nucleolar stress response." (PMID 31360909, 2019). "Because the impact of WDR5 and the MYC–WDR5 interaction on target RPG transcription is around two-fold, the self-limiting nature of WINi may provide a greater margin for safety than rRNA inhibitors that have to be dosed to split the difference between ribosome addiction in normal and cancer cells." (PMID 38202281, 2024). "Despite not being a direct WDR5 target gene, therefore, RPL22L1 expression is recurringly suppressed by WINi in responsive cancer cell lines." (PMID 38682900, 2024). "Therefore, to expand upon this, WDR5 depletion, combined with chemotherapeutics, could be considered as a promising candidate strategy in anti-CRC therapy to improve clinical outcomes by disrupting stem-like traits of cancer cells and amplifying the toxic effects of chemotherapeutics." (PMID 37708089, 2023). "Subsequently, however, it became clear that MLLr cancers are not dependent on MLL1, but instead rely on MLL2 —notable in this case because, although MLL2 complexes with WDR5, it does not depend on Win site binding for methyltransferase activity." (PMID 29385767, 2018). "Of note, the WDR5 or G9a dependency was not dependent on MYCN amplification status, which is possible due to the high expression of c-Myc in MYCN non-amplified NB cell lines, while WDR5 and G9a have been shown to mediate c-MYC function in the other types of cancers." (PMID 37781575, 2023).